USP8 (ubiquitin specific peptidase 8)
Diseases named in the same sentence as USP8 in open-access papers (continued):
Sharing a sentence is not in itself a finding about the gene and the disease.
corticotroph adenomas (continued). "The current case identifies a novel RASD1 mutation in a USP8-positive corticotroph adenoma." (PMID 28487882, 2017). "The results of the transcriptomic analysis and our hypothesis on the interaction between different pathways in USP8-mutated corticotropinomas need to be confirmed in additional experimental works with in vitro cellular models, and this is in the scope of our future investigations." (PMID 39684597, 2024). "Martins and colleagues conducted a study to investigate the USP8 variant and its contribution to gene expression of cell cycle regulators including P27/CDKN1B, CCNE1, CCND1, CDK2, CDK4, and CDK6 in 32 corticotroph adenoma." (PMID 38862897, 2024). "Of the eighteen patients with USP8-mutant corticotropinomas, the recurrence of pituitary adenoma growth was detected in eight (44%) cases, and among nine patients with USP8-WT tumors, the continued growth of pituitary adenomas was confirmed in two (22%) cases." (PMID 39684597, 2024). "An unexpected finding was positive SST2 expression in the majority of USP8-mutant corticotropinomas (in eight of eleven cases) and in three of the ten USP8-WT tumors." (PMID 39684597, 2024). "Despite the similar levels of ACTH and cortisol in the patients with USP8-mutant and USP8-WT corticotropinomas, the mortality and necessity of BLAE were perceived in the WT group." (PMID 39684597, 2024). "In this systematic review we extracted the information regarding the USP8 variant and the EGFR system in corticotroph adenomas." (PMID 38862897, 2024). "Hyperactive mutations of Usp8 and Usp48 cause excessive ACTH secretion from corticotroph adenomas, implying that USP8 and 48 have the potential to modulate the hypothalamus-pituitary-adrenal axis under physiological conditions." (PMID 36834633, 2023). "Recurrent mutations were reported in an additional deubiquitinase gene, USP48 (predominantly encoding p.M415I or p.M415V) in 21/91 paediatric subjects with corticotroph adenomas and in the BRAF gene (encoding p.V600E) in 15/91 subjects with wild-type USP8." (PMID 33515368, 2021). "Further, in corticotropinomas, EGFR overexpression is a consequence of 14-3-3 USP8 mutations, which are, in fact, quite specific to this tumor subtype." (PMID 34295309, 2021). "Gain-of-function mutations in USP8 have been implicated in aberrant EGFR signaling in corticotrophs and studies show USP8 mutations in 21-62% of corticotroph adenomas." (PMID 34867776, 2021). "With the understanding of the importance of USP8 in corticotropinomas, further studies for other genes related to the MAPK pathway have been published." (PMID 31877737, 2019). "However, the potential genetic risk of USP8 wild-type corticotroph adenomas remains unknown." (PMID 30093687, 2018). "Biochemical parameters such as ACTH levels of degree of hypercortisolism were similar, but the secreting ability of USP8-mutated tumors was proportionally higher (e.g., higher ACTH levels compared with size) than other corticotroph adenomas." (PMID 29765354, 2018). "To gain further insight into the molecular mechanisms of the pathogenesis of USP8 wild-type corticotroph adenomas, we conducted exome-sequencing of 22 paired tumor tissues and peripheral blood samples." (PMID 30093687, 2018). "Notably, our patient's adenoma had the USP8 p.P720R mutation that has previously been described as involved in the pathogenesis of CD, occurring in 35%–62% of CD-causing corticotroph adenomas; this was also the sole mutation identified in the ClinVar cross-reference." (PMID 28487882, 2017). "Herein, we found USP8 pathogenic variants in 15.8% of our samples supporting that USP8 gene defects do not explain the majority of pediatric corticotropinomas." (PMID 40813536, 2025). "Further research is needed to determine whether sex-specific genetic, epigenetic, or hormonal factors drive the emergence of USP8-mutant tumors, and whether this contributes directly to the gender disparity in corticotropinomas’ incidence." (PMID 40364036, 2025).
corticotroph adenomas (continued). "Another study of patients with 134 functional and 11 silent corticotroph adenomas demonstrated somatic USP8 variants only in functional adenomas, none of them occurred in silent adenomas." (PMID 38862897, 2024). "The aim of this study was to evaluate clinical data of a cohort of CD patients with different USP8 mutation statuses and to perform transcriptome analysis of tumor tissue to define USP8-related molecular mechanisms determining the biological features of corticotropinoma." (PMID 39684597, 2024). "Exosome sequencing of 18 USP8 non-mutated corticotroph adenomas (Cushing disease, n = 15; Nelson’s tumors, n = 3) indicated that the prevalence of USP48 mutations was 17% (3 samples)." (PMID 36834633, 2023). "Indeed, chemical compounds such as compound 9-oxo-9H-indeno [1,2-b]pyrazine-2,3-dicarbonitrile (DUBs-IN-2) and RA-9 have been described as USP8 inhibitors in the experimental models of corticotropinomas." (PMID 37109772, 2023). "Along these lines, USP8 variants are less frequently found in Crooke’s cell adenomas than in other corticotropinomas and do not seem to drive Nelson’s syndrome." (PMID 38067388, 2023). "Somatic BRAF V600E mutation has been reported in several tumors; in 2018, such a mutation was detected in 16.5% of a case series of USP8-WT corticotrope adenomas; this alteration was not mutually exclusive with USP48 mutations." (PMID 35743266, 2022). "Regarding the genetic cause of SCAs, candidate genes have not yet been clarified, and the USP8 mutation commonly found in functioning and silent corticotroph adenomas." (PMID 34220707, 2021). "The mutational status of BRAF, USP8, and USP48 in corticotroph adenomas may be used in the future to characterize the molecular subtypes and guide targeted molecular therapy." (PMID 30093687, 2018). "Therefore, similar to USP8, BRAF and USP48 mutations appear to be unique genetic signatures of corticotroph adenomas." (PMID 30093687, 2018). "USP8 characterization is not widely available, but USP8-mutated corticotroph adenomas causing CD appear more frequently in women (70–95% females), are smaller in size (most tumors are <0.5 cm) and are less radiologically invasive, compared with wild type." (PMID 29765354, 2018). "Moreover, Pasireotide as well as inhibitors of EGFR such as Gefitinib and Lapatinib, as well as USP8 inhibitors including -ehtyloxyimino9H-indeno (1, 2-b) pyrazine-2, 3-dicarbonitrile, DUBs-IN-2, and RA-9 indicated promising results in treatment of corticotroph adenomas." (PMID 38862897, 2024). "Additionally, the frequency of USP8 mutations in NS tumors and CD was comparable, demonstrating that USP8 mutations are not the cause of the development of corticotroph adenoma in NS." (PMID 37332454, 2023). "Thus, based on these favorable results on the AtT-20 cells, the blockade of USP8 might be useful for the treatment of human corticotropinomas, while further research should be conducted." (PMID 37109772, 2023). "Initially, corticotropinomas harboring USP8 variants were considered to exhibit a benign phenotype, based on initial observations that they tended to be smaller compared to wild‐type tumors and typically manifested as overt Cushing's disease rather than silent corticotropinomas." (PMID 39688352, 2024). "A favorable phenotype was originally proposed for corticotropinomas carrying USP8 variants because the first studies reported that they were smaller than their wild-type counterparts and because they almost always present with overt CD and not as silent corticotropinomas." (PMID 38067388, 2023). "Furthermore, recently identified somatic mutations in the deubiquitinases USP8 and USP48 occurs with greater frequency in women than men with Cushing’s disease, suggesting that the corticotrope adenoma itself may harbour features which contribute to gender-dependent differences in Cushing’s disease." (PMID 32183012, 2020).
corticotroph adenomas (continued). "Apart from HIFs, USP8 is involved in epidermal growth factor receptor (EGFR) turnover, thus rescuing EGFR from lysosomal degradation, and mutations in the USP8 gene have been found in corticotroph adenomas, which could cause Cushing’s disease via activation of EGFR signaling." (PMID 31208103, 2019). "Overexpression of SSTR5 has recently been reported among USP8-mutated corticotrope adenomas compared to wild-type adenomas; however, USP8 mutations were found in adenomas from female patients only, thus this finding could be gender- rather than USP8-variant specific." (PMID 32183012, 2020). "Recently, USP48 and BRAF have been reported as additional target genes, with somatic variants of BRAF gene in 16% of patients and of USP48 gene in 23% of USP8-negative corticotropinomas." (PMID 31877737, 2019). "Furthermore, the maximum diameter of all USP8-mutant corticotropinomas did not exceed 2 cm, while about 40% of USP8-WT tumors were >2 cm." (PMID 39684597, 2024). "However, dysregulation of USP8 in tumorigenesis may not be limited to corticotroph adenomas and additional USP8-mediated mechanisms may contribute to tumorigenesis." (PMID 31845722, 2019).
pituitary adenomas (20 papers, 2016 to 2025). "USP8 is linked to a variety of diseases, including pituitary adenomas, Cushing's disease, and esophageal squamous cell carcinoma." (PMID 40355913, 2025). "Its downregulation in PDD likely destabilizes lysosomal membranes, impairing proteostasis and exacerbating Lewy body pathology—a mechanism supported by studies linking USP8 mutations to pituitary adenomas via secretory vesicle dysregulation." (PMID 40355913, 2025). "In ACTH pituitary adenomas, USP8 mutations are also positioned within or in close proximity to the 14-3-3 binding motif (RSYSS)." (PMID 39456581, 2024). "The mutations in the USP8 gene are closely related to the development of pituitary adrenotropic hormone-secreting pituitary adenomas." (PMID 37239376, 2023). "This constellation of molecular alterations associated with USP8 mutations has led some authors to recommend categorizing of the mutational status of this gene in ACTH-secreting pituitary adenomas." (PMID 35743266, 2022). "The exome analysis on the ACTH-secreting pituitary adenoma revealed a p.Ser718Pro-USP8 somatic mutation." (PMID 34489873, 2021). "Germline USP8 mutation has been found in a paediatric case with recurrent Cushing’s disease and developmental delay, representing a syndromic form of pituitary adenomas." (PMID 33543431, 2021). "Mutational activation of USP8 underlies pathogenesis of pituitary adenoma/Cushing’s Disease and leukemia, and USP8 expression correlates with poorer prognosis of lung and other cancers." (PMID 32924931, 2020). "In human patients, somatic mutations in USP8 were identified as the underlying cause of adrenocorticotropic hormone (ACTH) releasing pituitary adenomas causing Cushing's disease (CD)." (PMID 31845722, 2019). "The finding that mutations in USP8 are associated with ACTH-secreting pituitary adenomas in CD has recently drawn much attention." (PMID 31845722, 2019). "Our findings on the role of UPS in POMC/ACTH turnover are of particular interest given the recent reports on gain-of-function mutations in the thiol protease deubiquitinase USP8 gene in patients with ACTH-secreting pituitary adenomas, i.e., Cushing’s disease." (PMID 29536250, 2018). "Canine ACTH-secreting pituitary adenomas lack mutations in the USP8 gene suggesting a different genetic background of pituitary tumourigenesis in dogs." (PMID 28005997, 2016). "Recently, hotspot recurrent mutations in the gene encoding for ubiquitin specific protease 8 (USP8) have been identified as the main driver behind the formation of ACTH-secreting pituitary adenomas in humans." (PMID 28005997, 2016). "Moreover, somatic USP8 gain-of-function mutations are common in ACTH-secreting pituitary adenoma causing Cushing’s disease." (PMID 35361799, 2022). "However, contrary to expectations, USP8-mutated pituitary adenomas displayed high immunoreactivity of USP8 in the nuclei, some of them exclusively, others at least partly." (PMID 31845722, 2019). "Moreover, studies have shown that pituitary adenomas with mutated USP8 display an increased incidence of EGFR expression, EGFR protein abundance and the mRNA expression levels of POMC, indicating that EGFR plays an important role in adenomaigenesis." (PMID 31798535, 2019). "Of the 18 patients with USP8-mutant pituitary adenomas, hypercortisolism remission was proved in 10 cases (55%)." (PMID 39684597, 2024). "Considering that pituitary adenomas in children can be genetically predisposed (e.g., MEN 1 mutation, AIP mutation, USP8 mutation, and other rarer ones), genetic consultation was sought." (PMID 37762908, 2023). "The identification of nuclear USP8 targets has become particularly important in view of the high immunoreactivity of mutant USP8 in the nuclei of ACTH-secreting pituitary adenomas." (PMID 31845722, 2019).
pituitary adenomas (continued). "Although USP8 mutations have not been identified in canine ACTH-secreting pituitary adenomas, increased nuclear expression of USP8, similar to that observed in USP8-mutated human tumors, has been reported in dogs, correlating with smaller tumor size but elevated ACTH production." (PMID 40943544, 2025). "Exome sequencing excluded a causative germline mutation but showed somatic mutations of the β-catenin protein gene (CTNNB1) in the adrenal adenoma, and of both the ubiquitin specific peptidase 8 (USP8) and the glucocorticoid receptor (NR3C1) genes in the pituitary adenoma." (PMID 34489873, 2021).
lung carcinoma (18 papers, 2019 to 2025). "USP8 is associated with tumor development, including lung cancer, cervical cancer, cholangiocarcinoma, breast cancer, and hepatocellular carcinoma." (PMID 36338727, 2022). "USP8, the deubiquitinase required for entry into the S phase, is mutated at its disordered 14-3-3-binding motif, enhancing deubiquitinase activity in lung cancer." (PMID 33806614, 2021). "On the other hand, USP8 instead downregulates PD-L1 in lung cancer and CRC, and USP8 blockade increases the efficacy of ICB." (PMID 38715050, 2024). "The expression of USP8 is frequently overexpressed in multiple cancer types, including lung cancer, breast cancer, cholangiocarcinoma, gastric cancer and melanoma." (PMID 37311739, 2023). "For these reasons, the use of an USP8 inhibitor to overcome c-Met resistance in lung cancer can serve as a viable therapeutic option." (PMID 35631459, 2022). "For example, knockdown of USP8 in lung cancer cells inhibited the proliferation of lung cancer cells by regulating several cell cycle and apoptosis-related proteins." (PMID 34503235, 2021). "Two studies reported that USP8 is a novel target for overcoming gefitinib resistance in lung cancer." (PMID 34081623, 2021). "Through the bioinformatic analysis, we found that colon and lung cancer patients with low USP8 expression had significant upregulation of a panel of MHC-I pathway-related genes, which indicates a better survival when accompanied with a higher level of CTLs infiltration." (PMID 35361799, 2022). "USP8, a member of the largest deubiquitinase (USP) family, has been associated with the development of a variety of cancers, including breast cancer, lung cancer, and cervical squamous cell carcinoma, as previously stated." (PMID 36338727, 2022). "A previous study showed that USP8 regulates c-Met-mediated degradation in lung cancer." (PMID 35631459, 2022). "Interestingly, functional studies showed that USP8 can enhance tumor initiation and progression of lung carcinoma, likely stabilizing receptor tyrosine kinases (RTK), such as EGFR or p-MET, through the interaction with stratifin (SF), a recently identified oncogene." (PMID 31487906, 2019). "USP8, belonging to the USP protease family, is increased in multiple kinds of cancers, including melanoma, gastric cancer, liver cancer, and lung cancer." (PMID 40862294, 2025). "Liu Shuang and colleagues investigated lncRNA-microRNA interactions, chromatin modifiers, and ferroptosis in lung cancer, as well as the oncogenic role of GINS4, the tumor-suppressive function of GPR162 in radiotherapy, the impact of AhR on NSCLC, and the targeting of USP8 in HCC treatment." (PMID 39944353, 2024). "Moreover, the inhibition or the reduced expression of USP8 selectively eliminates gefitinib-resistant and -sensitive non-small cell lung cancer, representing a novel direction for drug development for CSCC and lung cancer therapy." (PMID 31487906, 2019). "Interestingly, USP8 has also been studied in other tumors and been found to be upregulated in cervical squamous cell carcinoma and lung carcinomas, representing a negative prognostic factor, even though its mutations remain specific markers of corticotrope adenomas." (PMID 35743266, 2022).